SLC7A11 (solute carrier family 7 member 11)
Diseases named in the same sentence as SLC7A11 in open-access papers (continued):
Sharing a sentence is not in itself a finding about the gene and the disease.
neurological disorders (5 papers, 2021 to 2024). "The results of this study highlight the pivotal functions of SLC7A11 and astrocytes in modulating ferroptosis, paving the way for novel strategies in the treatment of neurological diseases." (PMID 39724413, 2024). "The function of SLC7A11 as an antiporter releasing glutamate is intriguing in the context of studying valpromide as a drug used to treat neurological disorders since glutamate is a neurotransmitter." (PMID 38635661, 2024). "Accordingly, genetic deletion of the specific subunit xCT (Slc7a11; xCT−/− mice) is protective in mouse models for (age-related) neurological disorders characterized by excitotoxicity and neuroinflammation." (PMID 35181756, 2022).
kidney (4 papers, 2022 to 2024). "Here, we confirmed that the downregulation of SOD, GSH, and GPX4 levels; the upregulation of Slc7a11, Acsl4, Cox2, 4-HNE, MDA, and Fe2+ levels; and kidney dysfunction all occur in the AKI mouse model." (PMID 35979396, 2022).
bacterial infection (3 papers, 2015 to 2025). "In fact, we observed that F. nucleatum modulates the cystine/glutamate antiporter in an OSCC cell line by increasing SLC7A11 expression, promoting L-glutamate efflux and favoring bacterial infection." (PMID 39743544, 2025). "We then employed an endotoxemia model as a simulation of systemic bacterial infection with a ligand that heavily induces Slc7a11 expression in macrophages." (PMID 37792774, 2023). "In summary, our data suggest that the System xc- (SLC7A11 and SLC3A2) is exacerbated by the presence of F. nucleatum, promoting more L-Glutamate efflux and bacterial infection." (PMID 39743544, 2025).
immune diseases (3 papers, 2023 to 2024). "SLC7A11 imports cysteine for glutathione biosynthesis and antioxidant defense and is overexpressed in multiple human and immune diseases." (PMID 39123125, 2024). "The prediction of the efficacy of immunotherapy with TICA and TIDE databases proved that the lower SLC7A11 level has a better curative effect of anti-PD-1/PD-L1 and anti-CTLA4 treatment and less probability of immune escape and immune dysfunction." (PMID 37713821, 2023). "Given the specific subcellular localization of SLC7A11 and its recognized functional significance, it is not unexpected that a multitude of studies have consistently demonstrated the involvement of SLC7A11 in various neurodegenerative, ocular, and immune disorders." (PMID 39040097, 2024).
hematologic malignancies (2 papers, 2021). "First, SLC7A11 is rarely expressed in hematologic malignancies (AEL, AML, and ALL)." (PMID 34938318, 2021).
respiratory diseases (2 papers, 2021 to 2024). "However, expression levels of SLC7A11 and GPX4 differ in a variety of respiratory diseases." (PMID 38562175, 2024).
brain diseases (1 paper, 2023). "SLC7A11 and FTH1 also play important roles in many brain diseases associated with ferroptosis." (PMID 38203455, 2023).
SLC7A11 also shares sentences with these, for which no sentence is quoted: adrenocortical carcinoma (7 papers); Burkitt lymphoma (7); Hepatic steatosis (6); rectum adenocarcinoma (5); small cell lung carcinoma (5); cyst (4); tuberculosis (4); cerebral infarction (3); coronary artery disease (3); prostate adenocarcinoma (3); tongue cancer (3); uterine corpus endometrial carcinoma (3); /T-cell lymphoma (2); AIDS (2); alcohol (2); Arthritis (2); cardiac diseases (2); cardiovascular disease (2); chronic obstructive pulmonary disease (2); colorectal adenocarcinoma (2); experimental autoimmune encephalomyelitis (2); gastric ulcer (2); laryngeal squamous cell carcinoma (2); lupus nephritis (2); ovarian clear cell cancer (2); primary effusion lymphoma (2); ulcers (2); uterine serous carcinoma (2); abdominal aortic aneurysm (1); acute lymphoblastic leukemia (1).
A further 81 diseases each share a sentence with SLC7A11 in 1 paper.